BRCA1 (BRCA1 DNA repair associated)
Diseases named in the same sentence as BRCA1 in open-access papers (continued):
Sharing a sentence is not in itself a finding about the gene and the disease.
invasive breast carcinoma (98 papers, 2005 to 2026). A carcinoma that infiltrates the breast parenchyma. "We performed a semi-quantitative IHC analysis of BRCA1 protein expression in a targeted cohort of 100 invasive breast carcinomas, enriched for TNBC (88%) and BRCA1 mutation carriers (34%)." (PMID 41751865, 2026). "While BRCA1/BRCA2 pathogenic sequence variants (PSVs) clearly confer an increased risk for invasive breast cancer, the extent to which these mutant alleles increase DCIS risk is less clear." (PMID 36349178, 2022). "Overexpression of EZH2 is able to activate the PI3K/AKT pathway, by which BRCA1 (a tumor suppressor) were exported from nuclei, and aneuploidy and mitotic deficiency were elicited, leading to invasive breast cancer." (PMID 34257531, 2021). "We set up cohorts of patients with invasive breast cancers and documented germ-line BRCA1 and BRCA2 pathogenic variant statuses." (PMID 32290274, 2020). "Increased expression of EZH2 associates with decreased nuclear expression of phospho-BRCA1 (Ser1423) and upregulation of phospho-Akt-1 (Ser473) in ~ 40% of invasive breast carcinomas." (PMID 33330580, 2020). "In 1999, we initially reported that our prospective findings indicated that carriers of the most frequent path_BRCA1 variants had lower incidence for infiltrating breast cancer than other path_BRCA1 carriers." (PMID 30678073, 2019). "Approximately 1 in 8 women (~12.4%) will develop invasive breast cancer over the course of their lifetimes, whereas the estimated average cumulative risk for these cancers by age 70 among BRCA1 carriers is 60%." (PMID 30652068, 2018). "Twelve carriers had a history of invasive breast cancer and chemotherapy (nine BRCA1 and three BRCA2 mutation carriers), and 51 carriers were excluded for other reasons." (PMID 28831696, 2017). "A more recent study from the same group, found that 5.3% of French Canadian women with invasive breast cancer had one of six recurrent BRCA1/BRCA2 mutations." (PMID 25925845, 2015). "The CIMBA Consortium analyzed the pathology of invasive breast cancers in 6,893 BRCA1/2 mutation carriers, and found that only 2.2% of tumors associated with BRCA1 were ILC." (PMID 25848941, 2015). "It has been reported that 10–36% of BRCA1 mutation-related invasive breast cancers are, in fact, ER+." (PMID 24137399, 2013). "It appears that many women diagnosed with an invasive breast cancer associated with a BRCA1/2 mutation or a strong family history choose mastectomy as their definitive surgical therapy in lieu of breast conservation with irradiation." (PMID 22295226, 2011). "Relative amounts of mutated and wt BRCA1 DNA were measured by quantitative polymerase chain reaction performed on laser capture microdissected cancer cells from 42 ER+ and 35 ER- invasive breast cancers that developed in BRCA1 carriers." (PMID 21080930, 2010). "This difference may be explained by the fact that BRCA1 mutations predispose much strongly to invasive breast cancers than to DCIS." (PMID 40770660, 2025). "However, the effect of such differential distribution of BRCA mutations on our results is likely to be minimal as only about 10% of Swedish women with family history of invasive breast cancer have been reported to have a BRCA1/2 mutation." (PMID 33148280, 2020). "A recent study, in which 289 self-identified AA patients, all of whom had been diagnosed with primary invasive breast cancer, were evaluated for a variety of germline mutations, including BRCA1 mutations, found that 80% of these patients carried mutations in their BRCA1 and BRCA2 genes." (PMID 33860286, 2019). "All miRNAs selected for qRT-PCR validation, except miR-1287, were differentially expressed in the same direction in qRT-PCR as in microarray analysis between the invasive breast carcinomas and the asymptomatic normal breast tissues of BRCA1 and BRCA2 germ-line mutation carriers." (PMID 26378051, 2015). "Ninety-eight BRCA1-associated ER+ and ER- invasive breast cancers were used for this analysis." (PMID 21080930, 2010).
invasive breast carcinoma (continued). "In each group, seven patients underwent prophylactic mastectomy because of a BRCA1 or BRCA2 gene mutation, while four patients underwent mastectomy following a diagnosis of invasive breast cancer." (PMID 40788543, 2025). "For BRCA1, recurrent mutations were detected in 1.2% of DCIS cases compared to 3.6% in invasive breast cancer cases." (PMID 40770660, 2025). "The proportion of BRCA1 and BRCA2 mutation carriers is high among patients with young-onset (aged 18–40 years) invasive breast cancer cancer." (PMID 37644384, 2023). "Based on the Breast Invasive Carcinoma (TCGA, Cell 2015) samples and studies, with clinical data from 816 patients, we queried the database for BRCA1/2." (PMID 35409110, 2022). "One BRCA1 PV carrier’s invasive breast cancer was diagnosed at age 27, 2 years older than the recommended age to begin screening (age 25)." (PMID 35323371, 2022). "The UK prospective cohort (POSH) study assessed OS in 2,733 women below 40 years of age at first diagnosis with invasive breast cancer harboring BRCA1/2m." (PMID 35909902, 2022). "The mean age of first invasive breast cancer diagnosis in BRCA1/2 heterozygotes (43.6 years) was significantly younger than that of wild-types (53.0 years, p < 0.001)." (PMID 32300229, 2020). "It has been found that the downregulation of EZH2 decreases invasive breast cancer and requires BRCA1." (PMID 31213036, 2019). "The 148 patients were identified until June 2003 as carrying BRCA1 or BRCA2 mutations with previous histories of unilateral, stage I–IIIa invasive breast cancer." (PMID 30203341, 2018). "The expression levels of CGB5, CGB7 and BRCA1 from breast invasive carcinoma study (TCGA, Cell 2015) is represented as heat map." (PMID 28869585, 2017). "Although BRCA1 and BRCA2 germline mutation-related invasive breast cancers are different in many ways, the hypoxia-related proteins HIF-1α, CAIX and Glut-1 are expressed in both DCIS and invasive lesions of BRCA1 and BRCA2 mutation carriers." (PMID 23409121, 2013). "We also examined the association with rs2180341 in women with BRCA1 or BRCA2 mutations based on data from 2,776 invasive breast cancer cases and 2,605 unaffected carriers." (PMID 22768030, 2012). "Since our data does not indicate differential E-cadherin expression and localization between sporadic and BRCA1-related invasive breast cancer, this cannot explain the increase in nuclear Kaiso localization." (PMID 22662240, 2012). "9,815 BRCA1 and BRCA2 mutation carriers were censored at a first invasive breast cancer diagnosis, of whom 4,310 had information on either ER or PR." (PMID 22053997, 2011). "Clinical characteristics of BRCA1 carriers with 58 ER+ and 114 ER- first invasive breast cancers were compared." (PMID 20149218, 2010). "The sensitivity and specificity of evaluating serum anti-BRCA1 AAbs were 8% and 91%, respectively, for invasive breast carcinoma, and 3% and 91%, respectively, for ductal carcinoma in situ." (PMID 21113302, 2010). "A population of 68 BRCA1 related invasive breast cancers was evaluated for LVI by an experienced breast pathologist blinded to mutation status, and compared to a control group matched for age, grade and tumor type." (PMID 20398395, 2010). "BRCA1 carriers aged ≥ 50 at diagnosis of first invasive breast cancer were more likely to have an ER+ cancer compared to those aged < 50 (57% vs 29%, P = 0.005)." (PMID 20149218, 2010). "The prevalence of BRCA1 and BRCA2 mutations among all women diagnosed with an invasive breast cancer or ductal carcinoma in situ is similar, and varies between 0.4–2.6% and 1.4–2.4%, respectively." (PMID 16909138, 2006). "We identified a cohort of 148 female BRCA1 or BRCA2 mutation carriers (115 and 33, respectively) who previously were treated for unilateral invasive breast cancer stages I–IIIa." (PMID 16052221, 2005).
invasive breast carcinoma (continued). "This case report describes a 56-year-old female with invasive breast cancer without estrogen or progesterone receptor expression, with apocrine differentiation, and with no germline variants in the BRCA1 and BRCA2 genes." (PMID 37583932, 2023). "A total of 8396 patients (mean [SD] age, 50.8 [11.4] years) with primary invasive breast cancer (stages I-III), including 491 BRCA1/2 variant carriers (5.8%) (187 BRCA1 carriers [2.2%] and 304 BRCA2 carriers [3.6%]) and 7905 noncarriers (94.2%), were included in the final analyses." (PMID 33890992, 2021). "Through retrospective review, we identified 501 patients who underwent breast‐conserving surgery, with 63 BRCA1/2 mutation carriers and 438 noncarriers with invasive breast cancer in this study." (PMID 31912664, 2020). "(2017) reported that AJ women diagnosed with invasive breast cancer, without a BRCA1/2 founder mutation, have a remaining 1% chance of having a non‐founder BRCA1/2 pathogenic mutation; if she is diagnosed before 40 years of age this chance increases to 3%." (PMID 30152102, 2018). "We genotyped the FANCM c.5791C>T mutation in 4806 invasive breast cancer patients, including BRCA1/2 mutation negative familial cases and unselected cases, and in 2734 healthy population controls from four different geographical areas of Finland." (PMID 28702895, 2017). "Less than 10% of invasive breast cancers are due to a BRCA1 mutation and therefore it is unlikely that the predictive capacity of the BRCA1-mutation DNAme signature in the NSHD cohort was due to the correct identification of BRCA1 mutation carriers." (PMID 25067956, 2014). "Future research will have to determine if and how other (p120-unrelated) events such as promoter methylation of specific genes may recruit Kaiso to the nucleus and initiate subsequent epigenetic silencing in BRCA1-related invasive breast cancer." (PMID 22662240, 2012). "Moreover, significant decreases in expression were observed for BRCA1, PP1β and PP1γ when comparing normal breast tissue with invasive breast cancers." (PMID 17511879, 2007). "Therefore, in the present study, the efficacy of CPM was investigated in a group of women with pathogenic BRCA1 or BRCA2 mutations and a personal history of unilateral invasive breast cancer." (PMID 16052221, 2005). "The clinical outcome of contralateral prophylactic mastectomy (CPM) in women with a BRCA1 or BRCA2 mutation and a personal history of invasive breast cancer is unknown." (PMID 16052221, 2005). "To investigate the value for FOXPs to distinguish Breast Invasive Carcinoma samples from normal smples, we performed a ROC curve analysis using ERBB2, BRCA1 and BRCA2 as controls." (PMID 35614183, 2022). "In the present study, we examined the subcellular expression of NHERF1, BRCA1 and PARP1 proteins in invasive breast carcinomas and investigated, for the first time, the relationship among their expression and with patient outcome." (PMID 29029467, 2017). "The analysis was restricted to carriers diagnosed with invasive breast cancer (326 BRCA2 and 40 BRCA1)." (PMID 26857456, 2016). "Analyses was restricted to the 392 (BRCA1) and 179 (BRCA2) population-based individuals diagnosed with a first primary invasive breast cancer before 40 years of age for whom BRCA1 and BRCA2 had been sequenced." (PMID 20807450, 2010). "AAbs to BRCA1 and BRCA2 protein were identified by ELISA in the sera of 8/94 (8.5%) and 32/94 (34%) invasive breast carcinoma patients, respectively, and 1/40 (2.5%) and 9/40 (22.5%) ductal carcinoma in situ patients, respectively." (PMID 21113302, 2010). "Consistent with BRCA1 being a downstream target of IRX5, there was significant correlation between BRCA1 and IRX5 gene expression in breast-invasive carcinoma, suggesting that the regulatory relationship between IRX5 and BRCA1 extends beyond epidermal keratinocytes." (PMID 37084727, 2023).
invasive breast carcinoma (continued). "Using TCGA publicly available expression profiles of cancer patients, we found that BRCA1 and BRCA2 were widely expressed in multiple tumors compared with normal tissues, including breast invasive carcinoma (BRCA), liver hepatocellular carcinoma (LIHC), and rectum adenocarcinoma (READ)." (PMID 32879886, 2020). "Interestingly, a positive correlation between ATM, ATR, BRCA1, BRCA2, and KMT2C expression is also derived from TCGA data GBM, LGG, AML, DLBL, SARC, and breast invasive carcinoma (BRIC) RNA‐seq data." (PMID 30665945, 2019).
serous carcinoma (80 papers, 2006 to 2025). "The presence of genomic instability, mainly driven by mutations in BRCA1/2 as well as other genes of the homologous recombination repair pathway, determines pathogenesis in high-grade serous carcinomas and to a lesser extent high-grade endometrioid carcinomas." (PMID 39940415, 2025). "A patient with a serous carcinoma harboring a BRCA1 mutation was treated with niraparib after the progression of the disease with whole-brain radiotherapy (WBRT) plus temozolomide, achieving survival of 13 months from the onset of BMs." (PMID 39941769, 2025). "High-grade serous carcinomas were by far the most prevalent, and among this group, recurrent variants were reported in both the BRCA1 (c.1674del, c.3331_3334del, and c.5123C>A) and BRCA2 (c.3860del) genes, detected at the germline and/or somatic level." (PMID 40710012, 2025). "Approximately 20%–25% of all high-grade serous carcinoma cases are caused by germline mutations in genes called BReast CAncer gene 1 (BRCA1) and BReast CAncer gene 2 (BRCA2)." (PMID 37519818, 2023). "Most BRCA1/2 pathogenic variants were detected in women diagnosed with high-grade serous carcinoma (110/129; 85%), although this was the commonest histological subtype tested (623/702; 89%)." (PMID 36765687, 2023). "Approximately 20%–25% of high-grade serous carcinoma cases are caused by germline mutations in the BRCA1 and BRCA2 genes." (PMID 37519818, 2023). "This is best exemplified by the synthetic lethal use of poly (ADP-ribose) polymerase-1/2 inhibitors (PARPi) to treat high-grade serous carcinomas that harbour a BRCA1 or BRCA2 pathogenic/likely pathogenic variant." (PMID 38201604, 2023). "Germline BRCA1/2 pathogenic variants occur in 22.6% of high-grade serous carcinomas (HGSCs), while somatic BRCA1/2 pathogenic variants have been shown in an additional 6–7% of HGSCs." (PMID 36011309, 2022). "The most common histological subtype was serous carcinoma and BRCA1 mutation appeared to be more frequent compared to BRCA2, as previously reported in the literature." (PMID 36011033, 2022). "As expected, and in accordance with our previous results from a study cohort overlapping with the present cohort, BRCA1/2 alterations were a hallmark of high-grade serous carcinomas." (PMID 33947352, 2021). "In our study, we found 33.3% (n = 6) BRCA1 pathogenic variants in high grade serous carcinoma which is in the range of foreign studies." (PMID 33773534, 2021). "For patients with high-grade serous carcinomas, the therapeutically well characterized genes BRCA1/2 harbored variants in half of patients with DNA repair pathway actionability (30%, n = 11)." (PMID 33947352, 2021). "Two cases of high grade serous carcinoma aged 36 and 70, with family history of cancer, have been detected of BRCA1 pathogenic variants, frameshift duplication p.Tyr655ValfsTer18 (rs80357522) and missense p.Arg1203Ter (rs62625308) respectively." (PMID 33773534, 2021). "It is generally recommended that every tubo-ovarian/primary peritoneal high-grade serous carcinoma be tested for at least somatic BRCA1/2 gene mutations, in addition to mutations in other high-risk genes." (PMID 33117676, 2020). "BRCA1/2 mutations in HG serous carcinomas were more than twice as frequent (146/472; 30.9%) as in LG serous ones (11/84; 13.1%)." (PMID 32295079, 2020). "We confirmed the association between the BRCA1/2 positive status and high-grade serous carcinoma histological subtype." (PMID 31653094, 2019). "The majority of mutations, variants, and epigenetic modifications in BRCA1 are reported in the high-grade serous carcinoma samples." (PMID 29997359, 2018). "Regarding OC patients with a BRCA1 mutation, 67% were high grade serous adenocarcinoma, and 33% were undifferentiated." (PMID 27741520, 2016). "The frequencies of BRCA1/2 pathogenic mutations in the entire cohort and the subgroup of patients with serous carcinoma were 12.1% (12/99) and 26.1% (12/46), respectively." (PMID 27907908, 2016).